NLRC4 (NLR family CARD domain containing 4)
Diseases named in the same sentence as NLRC4 in open-access papers (continued):
Sharing a sentence is not in itself a finding about the gene and the disease.
tumor (continued). "Similar to pyroptosis, the effects of NLRC4 depend on the type and genomic background of the tumor." (PMID 35928454, 2022). "The obese tumor microenvironment favors the recruitment of macrophage and the activation of NLRC4 inflammasomes in these cells promotes the production of adipocyte-originated growth factor vascular endothelial growth factor-A (VEGF-A), thereby promoting angiogenesis." (PMID 34276697, 2021). "The differential but variable expression of NLRC4 has been observed in a variety of tumor tissues." (PMID 34276697, 2021). "In addition to this study, it was found that the production of cytokines (IFN-γ) and chemokines (CXCL9, CXCL10, CXCL16, and CCL5), which contribute to tumor growth, were reduced in Nlrc4-/- mice." (PMID 34276697, 2021). "For example, obesity induces an increase in tumor-infiltrating MDSCs with activated NLRC4 inflammasome, leading to IL-1β production, which drives tumor progression through adipocyte-mediated vascular endothelial growth factor (VEGF) A expression and angiogenesis." (PMID 31182982, 2019). "Although NLRC4 was implicated to have effects of tumor suppression, another two groups argued that NLRC4 has no roles or even a negative role in anticancer immune responses." (PMID 28360909, 2017). "Similarly, E0771 tumour growth in Nlrc4−/− DIO mice was significantly reduced compared with their WT DIO counterparts (P=0.001, two-way ANOVA)." (PMID 27708283, 2016). "Although the NAIP5/NLRC4 inflammasome-mediated IL-1β secretion in response to the injection of flagellin-modified tumor cells, it is unclear whether the involvement of this cytokine was necessary for the success of this immunotherapy." (PMID 25071770, 2014). "Interestingly, Nlrc4−/− and caspase-1−/− mice exhibited increased tumor formation compared to wild-type mice." (PMID 24273542, 2013). "Nlrc4−/− mice receiving a wild-type bone marrow transplant had similar tumor loads as Nlrc4−/− mice receiving Nlrc4−/− bone marrow in the CAC model, but exhibited significantly higher tumor burdens than wild-type mice receiving either wild-type or Nlrc4−/− bone marrow." (PMID 24273542, 2013). "AIM2, CASP3, NLRC4, TNF, and NLRP6 may be associated with tumour drug resistance." (PMID 35246158, 2022). "In contrast to Py8119 tumours, E0771 tumour growth was also reduced in Nlrc4−/− relative to WT mice with ND, suggesting a slightly different phenotype and indicating that the NLRC4 inflammasome could be also important for tumour growth in non-obese condition for certain cancers." (PMID 27708283, 2016). "To explore the capability of tumor-cell-derived NLRC4 expression to directly mediate DC maturation for T cell activation, we cocultured HT29-NLRC4 cells with freshly isolated human primary DCs from human blood." (PMID 38652550, 2024). "The activation of the NLRC4 inflammasome can also boost the production of inflammatory substances in HCC and influence tumor cell malignant development." (PMID 38780447, 2024). "Thus abnormal NLRC4 activation in TME may facilitate tumor metastasis." (PMID 36932407, 2023). "Immunohistochemistry (IHC) was used to evaluate the differential expression of major PRGs (GSDMC, GSDMD, GSDME, NLRP3, NLRC4, IL1B) in selected tumor types (COAD, HNSC, KIRC, LIHC, LUAD, LUSC)." (PMID 36605187, 2022). "The NLRC4/IL-1β module was able to promote angiogenesis via up-regulation of VEGFA, which in turn to contributed tumor progression." (PMID 33987528, 2021).
tumor (continued). "Tumor-related macrophages (TAMs) are a major part of the tumor microenvironment that promotes tumor growth, and NOD-like receptor C4 (NLRC4) is a component of the inflammatory body complex." (PMID 32181157, 2020). "Several genes encoding core inflammasome components were all significantly expressed at higher levels in ACP tumours compared with control tissues, including NLRP1 (6.4-fold), NLRP3 (4.8-fold), NLRC4 (4.8-fold), CASP1 (5-fold) and PYCARD (4-fold) [Suppl." (PMID 29541918, 2018). "In sum, these results obtained from the TCGA database indicate that across tumor stages, NLRP1, NLRP3, NLRC3, NLRC4 and AIM2 expression in CRC tissues was significantly less than healthy controls." (PMID 26378020, 2015). "Despite the well-known role of TLR5, the recognition of flagellin by the NAIP5/NLRC4 inflammasome was also required for the induction of a protective CD8+ T cell response and tumor suppression." (PMID 25071770, 2014). "Mice lacking caspase-1 or NLRC4 exhibited greater proliferation of colonic epithelial cells and decreased apoptosis of tumor cells, which led to an increase in tumor formation in colitis-associated colorectal cancer models." (PMID 40141358, 2025). "We identified that tumor epithelial expression of NLRC4, rather than stromal, is critical to mediate immune protection through DC and CD4+ and CD8+ T cell immune infiltration into the tumor microenvironment." (PMID 38652550, 2024). "In comparison with mouse models, our results in patients are consistent with a previous study showing that Nlrc4–/– mice displayed increased colon tumorigenesis in the AOM/DSS model wherein tumors appeared aggressive, with invasion of tumor cells below the muscular mucosae." (PMID 38652550, 2024). "Multiple inflammasomes, including NLRP3, NLRC4, NLRP1, and AIM2, may inhibit tumor initiation by influencing innate and adaptive immunity, apoptosis, and differentiation." (PMID 36437954, 2022). "NLRC4 is critical for cytokine production in TAM and necessary for the generation of IFN-γ-producing CD4+ and CD8+ T cells in an inflammasome-independent manner, suppressing tumor growth in a subcutaneous murine model of melanoma." (PMID 35739593, 2022). "But similar to several other NLR proteins, NAIPs also suppress tumour formation in the colon, which appears to not require NLRC4 inflammasome signalling." (PMID 34854889, 2021). "This phenomenon may occur due to different genetic backgrounds, such as the generation of Nlrc4-/- mice on different sublines of C57BL/6, resulting in differences in tumor suppression." (PMID 34276697, 2021). "Here, we demonstrated that NLRC4 contributes to the induction of anti-tumor immunity and that TLR5 might play a role transporting flagellin fusion antigens into cells to activate cytosolic NLRC4 inflammasome signaling." (PMID 27063435, 2016). "We identified 4.1-fold increase in Nlrc4 mRNA but not Nlrp3 expression in tumours from DIO mice compared with those from ND mice." (PMID 27708283, 2016). "We found that Cxcl1 mRNA was elevated in tumours from obese mice but not in the NLRC4 inflammasome-dependent manner." (PMID 27708283, 2016). "Surprisingly, similar colitic phenotypes have been observed between WT and Nlrc4−/− mice following DSS administration, suggesting that tumor regulation by NLRC4 is mostly cell intrinsic and not through down-regulation of inflammation." (PMID 25071785, 2014). "Given the unique capacity of NLRC4 to sense and differentiate between commensal and pathogenic microbes in the gut, it is surprising that the tumor restraining roles of NLRC4 have been ruled to be independent of its immune regulatory functions." (PMID 25071785, 2014). "In addition, immunization with flagellin expressing cancer cells lead to impressive antigen-specific CD4 and CD8 T cell responses via NLRC4 and NAIP5 signaling and bestowed anti-tumor immunity against a secondary inoculation with tumor cells." (PMID 25071785, 2014).
tumor (continued). "We found that 25 out of the 33 tested inflammasome-related genes were detectable by quantitative RT-PCR, and 8 of them (CIITA, NLRC4, NLRP3, NLRP7, AIM2, RIG-I, ASC and IL-1β) were overexpressed (fold change, >2) in NPC tumour samples, compared to adjacent normal samples." (PMID 23065753, 2012). "Interestingly, another study used the same mouse model, but there was no discrepancy in neoplasm incidence between wild-type and Nlrc4-/- mice from the same litter." (PMID 37020871, 2023). "NLRC4 is expressed in immune and non-immune cells, including monocytes, macrophages, and neutrophils; nevertheless, differential expression of NLRC4 has been reported in many types of tumor tissue." (PMID 36437954, 2022). "Hence neither the reported expression or indeed role of NLRC4 in tumor regulation and suppression is always consistent, even in the same tumor type." (PMID 34276697, 2021). "In this study, we found that the pyroptosis genes including GSDMB, GSDME, NLRC4, NLRP2 and GZMA were hazardous genes in AML, and the genes of proinflammatory cytokines such as IL6 and TNF were found to be protective genes which maybe related with tumor microenvironment." (PMID 36553549, 2022). "One unifying theory addressing these discrepancies could be that anti-tumor functions of NLRC4 are attributed to the cells of non-hematopoietic origin, whereas intestinal mononuclear phagocytes are the primary source of NLRC4 for microbial sensing and pathogen clearance." (PMID 25071785, 2014). "There was very little Nlrc4 mRNA in tumours from Nlrc4−/− DIO mice, indicating that Nlrc4 is primarily expressed in the host but not in the cancer cells." (PMID 27708283, 2016). "Moreover, compared to wt mice, a significant increase in inflammatory features, tumor multiplicity, and max tumor size was found in AOM-DSS-treated Nlrp3−/− mice, but not in Nlrc4−/− mice." (PMID 29868004, 2018).
bacterial infection (51 papers, 2012 to 2025). "While NLRC4 activation is critical for activating the immune response and driving inflammation during bacterial infection, its overactivation can cause aberrant cell death and cytokine release." (PMID 33494299, 2021). "We tested bacterial infection in vivo and found that the Casp7/Gsdmd–/–mice are as susceptible as the Nlrc4–/–mice." (PMID 31251782, 2019). "The major function of the NAIP/NLRC4 inflammasome in vivo is to defend the host against bacterial infections, particularly those caused by bacteria possessing flagella and/or a T3SS, through the induction of inflammation involving the production of IL-1β and IL-18." (PMID 40158217, 2025). "Notably, the NLRC4 inflammasome is vital in bacterial infections within the liver, with NLRC4-mediated IL-1β release associated with liver inflammation." (PMID 38666950, 2024). "Some bacterial infections activate NLRC4 inflammasomes causing an inflammatory response." (PMID 34276697, 2021). "LRRK2 has been shown to promote the activation of the NLR family CARD domain-containing protein 4 (NLRC4) inflammasome, particularly during bacterial infections like Salmonella Typhimurium." (PMID 40309866, 2025). "While the NLRC4 inflammasome is primarily known for its role in immune defense against bacterial infections, its elevated expression in this context suggests a potential role in modulating neuroinflammatory responses relevant to cognitive function." (PMID 40573155, 2025). "The NAIP/NLRC4 inflammasome plays a pivotal role in the defense against bacterial infections, with its in vivo physiological function primarily recognized as driving inflammation in immune cells." (PMID 40158217, 2025). "Other monocyte informative genes were also activated in patients with bacterial infection including NLRC4, CYP1B1, PFKFB3, LILRA5, NFKBIA, and NFKBIZ." (PMID 40581066, 2025). "The NAIP/NLRC4 inflammasome senses bacterial infection and can be activated by treatment with a needle protein (LFn-BsaL) and protective antigen." (PMID 40892070, 2025). "Well-known inflammasome proteins, such as NLRP3 and NLRC4, and Casp4 are intracellular PRRs that induce pyroptosis during intracellular bacterial infections." (PMID 39951384, 2025). "Inflammasomes, particularly NLRC4, play crucial roles in immune responses to intracellular bacterial infections." (PMID 41116055, 2025). "The NLRC4 inflammasome is assembled in response to bacterial infections, and the activation requires the recognition of specific bacterial protein ligands by the NLR family of apoptosis-inhibitory proteins (NAIP)." (PMID 39684769, 2024). "In addition to ongoing research on NAIP/NLRC4 mutations contributing to both bacterial infections and sterile inflammation in autoimmune and inflammatory diseases, the interplay between NLRC4 and PUFA metabolites may open another window for developing new therapeutic strategies." (PMID 39290706, 2024). "The NLR family caspase activation and recruitment domain-containing 4 (NLRC4) inflammasome is a critical cytosolic innate immune machine formed upon the direct sensing of bacterial infection and in response to cell stress during sterile chronic inflammation." (PMID 38177670, 2024). "The NAIP/NLRC4 inflammasome in humans is crucial to the host immune response to bacterial infections and contributes to auto-immune and inflammatory diseases in a sterile condition." (PMID 38177670, 2024). "Several studies have shown the critical role of NLRC4 in the host’s defense against bacterial infections." (PMID 39684769, 2024). "NAIP/NLRC4 inflammasome activation during bacterial infection occurs after recognition of their ligands by NAIP proteins." (PMID 38124741, 2023). "Numerous studies have extensively investigated the immune functions of NLRC4 in response to bacterial infection." (PMID 36920176, 2023).
bacterial infection (continued). "Collectively, our findings shed light on the pivotal role of the NAIP/NLRC4 inflammasome in macrophage responses to T. cruzi infection, providing new insights into its broader functions that extend beyond bacterial infections." (PMID 38124741, 2023). "A similar reaction was observed in cultured intestinal epithelial cells in which a bacterial infection sensed by the NAIP/NLRC4 inflammasome induce a fast myosin-dependent contraction in surrounding cells." (PMID 37417734, 2023). "During bacterial infection, bacterial proteins in the cytoplasm are detected by NAIPs to activate the NLRC4 inflammasome, which results in the processing and activation of precursors of IL-1β and IL-18 cytokines for extracellular secretion." (PMID 36833425, 2023). "Recent studies have reported the involvement of NLRC4 in non-bacterial infections such as C. albicans, N. caninum and HIV infection." (PMID 38124741, 2023). "Whereas the mechanisms governing NAIP/NLRC4 inflammasome are better elucidated, primarily in the context of bacterial infections." (PMID 38124741, 2023). "The well-established role of NAIP/NLRC4 inflammasome in bacterial infections involves NAIP proteins functioning as sensors for their ligands." (PMID 38124741, 2023). "Since pyroptosis is often associated with inflammasome activation, we further tested the role of TREM2 on the activation of NLRP3 and NLRC4 inflammasome, which have been reported as the major inflammasomes induced by pyogenic bacterial infection." (PMID 36068223, 2022). "Increasing evidence in the literature demonstrate the participation of NLRC4 in inflammatory pathologies and non-bacterial infections." (PMID 36481780, 2022). "NLRC4 is another important inflammasome responses to pyogenic bacterial infection, especially for Pseudomonas aeruginosa infection." (PMID 36068223, 2022). "The involvement of NLRC4 in pathogen recognition was largely thought to be restricted to bacterial infections but recent studies revealed that dendritic cell NLRC4 regulates T cell response during influenza A virus infection." (PMID 34768828, 2021). "The expression of NAIPs and NLRC4 are regulated by the interferon regulatory factor 8 (IRF8) transcription factor during bacterial infection." (PMID 33494299, 2021). "For example, NLRP3 and NLRC4 are recruited to the same inflammasome complex to elicit inflammatory responses to bacterial infection or flagellin stimulation." (PMID 33446652, 2021). "In vivo, Irf8-deficient mice are highly susceptible to bacterial infection compared with wildtype animals, confirming the critical role of IRF8 in NAIP/NLRC4 inflammasome activation." (PMID 33494299, 2021). "The innate immune function of the NLRC4 inflammasome has been extensively studied during bacterial infections, especially the foodborne bacterium S. Typhimurium." (PMID 33494299, 2021). "NOD-like receptor family, CARD domain-containing 4 (NLRC4) is the most professional sensor molecule that responds to bacterial infections." (PMID 33312172, 2020). "Instead, NLRC4 inflammasome signaling by flagellated bacteria-released OMVs can contribute to rapid detection of bacterial infection leading to the inhibition of bacterial dissemination and virulence as a host defense mechanism." (PMID 33312172, 2020). "To date, various inflammasome members have been identified, among which NLRP3 and NLRC4 are the most common inflammasomes of the host innate immune system in sensing and reacting to bacterial infection." (PMID 29616195, 2018). "According to previous studies, various NLR-containing inflammasomes have been reported to be associated with bacterial infection, such as NLRP1, NLRP3, NLRC4, and NLRP6." (PMID 29616195, 2018). "The NAIP/NLRC4 inflammasomes presumably evolved to initiate protective immune responses during bacterial infection." (PMID 29263322, 2017).